EZHIP (EZH inhibitory protein)
Diseases named in the same sentence as EZHIP in open-access papers (continued):
Sharing a sentence is not in itself a finding about the gene and the disease.
cancer (8 papers, 2019 to 2026). A tumor composed of atypical neoplastic, often pleomorphic cells that invade other tissues. "The EZHIP gene becomes active following DNA demethylation in primordial germ cells and cancer cells." (PMID 35193659, 2022). "While we were completing this study, another publication reported the identification of EZHIP (CXORF67) as an inhibitor of PRC2 in two cancer cell lines (U2OS and Daoy Cells55)." (PMID 31451685, 2019). "Lastly, EZHIP has been implicated in DNA damage response in cancer, and this function is independent of the KLP motif." (PMID 41427323, 2025). "Previous studies have primarily focused on EZHIP’s role upon aberrant expression in cancer." (PMID 41427323, 2025). "Finally, our findings may also have implications for EZHIP’s role in cancer." (PMID 41427323, 2025). "Of 90 CTAs validated by RNA sequencing, eight CTAs (DPEP3, EZHIP, MAGEA4, MAGEB2, MAGEC2, PAGE1, PRAME, and TKTL1) were selected for immunohistochemical profiling in cancer tissues from 328 NSCLC patients." (PMID 37341056, 2023). "The core CT genes include CMTM1, CT83 (CXorf61), EZHIP (CXorf67), DCAF4L2, KHDRBS3, LEMD1, PIWIL1, and SPATA6, which contribute to cancer progression and metastasis." (PMID 33426787, 2021). "Indeed, fusions between EZHIP truncations and transcription factors have been predicted to result in aberrant PRC2 localization in cancers." (PMID 41427323, 2025). "EZHIP is often highly expressed in tumors that do not have an H3K27M substitution, suggesting that the cancer is either induced by an H3K27M mutation or high expression of EZHIP, which in both cases leads to reduced H3K27me3 levels." (PMID 35193659, 2022). "EZHIP prevents the deposition of H3K27me3, and is mis-regulated in various cancers which are hallmarked by a global lack of H3K27me344–47." (PMID 34880314, 2021).
CNS Tumors (3 papers, 2022 to 2025). "In addition to the K27M status, other changes, such as the overexpression of EZHIP and alterations in the epidermal growth factor receptor (EGFR), have been reported, which were recently included in the latest 2021 WHO classification of CNS tumors as “H3K27-altered tumors”." (PMID 36140466, 2022). "Firstly, since most of the patients (n = 153) were enrolled before June 2021, we did not include those who harbored EZHIP overexpression, which also results in a global reduction of H3K27me3 according to the 5th edition of the WHO Classification of CNS Tumors." (PMID 37311690, 2023).
EZHIP also shares sentences with these, for which no sentence is quoted: melanoma (2 papers); pituicytoma (2); bone cancer (1); diffuse astrocytoma (1); diffuse intrinsic pontine glioma (1); glioblastoma (1); glioneuronal tumour (1); Merkel cell carcinoma (1); neuroepithelial tumour (1); non-small cell lung carcinoma (1); oligodendroglioma (1); pilocytic astrocytoma (1); uterine neoplasms (1).